LEP (leptin)
Diseases named in the same sentence as LEP in open-access papers (continued):
Sharing a sentence is not in itself a finding about the gene and the disease.
colorectal cancer (continued). "Leptin increases chemo-resistance to 5-FU in pancreatic and colorectal cancers, resulting in increased tumor cell proliferation and reduced levels of pro-apoptotic factors, such as Bax, Caspase-3 and PARP." (PMID 33276524, 2020). "Compared to the lowest quintile of plasma leptin, the highest demonstrated a statistically significant increase in the BMI-adjusted OR of colorectal cancer (OR = 1.77; 95% CI, 1.00–3.16; P = 0.04)." (PMID 32053666, 2020). "MPS-1 was demonstrated to promote the leptin-induced growth of colorectal cancer via activating the JNK/c-Jun pathway." (PMID 33371368, 2020). "CRHR2 has been associated with endometriosis, localization of glucose transporters in the placenta, colorectal cancer, stress response in the cortisol pathway, and leptin responsiveness." (PMID 28417008, 2017). "There are contradictory reports on the pathobiological properties of leptin in the onset and progression of colorectal cancer." (PMID 28422056, 2017). "In most cancers, such as breast, prostate, lung and colorectal cancer, leptin acts as a growth factor that has the capability to promote cancer cell proliferation." (PMID 25948792, 2015). "In the context of the obtained results, it is necessary to extend studies of leptin and leptin receptors participation in the colorectal cancer initiation and transformation processes." (PMID 22363883, 2011). "It is necessary to extend studies of analysis of cellular signal transduction pathways by leptin in colorectal cancer initiation and transformation processes." (PMID 22363883, 2011). "The expression of leptin mRNA and protein by human breast and colorectal cancer cells and rat glioblastoma cultures has been documented previously." (PMID 21771332, 2011). "Similarly, leptin and adiponectin also influence macrophage cytokine expression and contribute to the progression of colorectal cancer via changes in gene expression within the PI3K/AKT pathway." (PMID 38611081, 2024). "Thus, in vitro experiments on colorectal cancer cells would be necessary to observe the effect of leptin on cancer development and progression." (PMID 36981858, 2023). "The results of this study suggest that leptin may be involved in the development of colorectal cancer." (PMID 36981858, 2023). "In summary, leptin levels were elevated in overweight and colorectal cancer patients." (PMID 36981858, 2023). "In conclusion, the results suggest that leptin may be involved in the development and progression of colorectal cancer." (PMID 36981858, 2023). "Our previus study suggests that Notch, IL-1, and leptin may serve a crucial role in the development of colorectal cancer." (PMID 38152619, 2023). "Potential mechanisms underlying this observation may be that LEP influences the growth and survival of CRC stem cells, and regulates the adhesion and invasion of colorectal carcinoma cells through activation of the JAK and ERK signaling pathways." (PMID 37282602, 2023). "Moreover, adiponectin and leptin results are consistent with previous meta-analyses of renal cell carcinoma, breast, and colorectal cancer, which further supports the credibility of our results." (PMID 35073877, 2022). "These evidence indicates that leptin could be a possible intermediary contributing to the association between the FTO rs9939609 polymorphism and colorectal cancer." (PMID 34650918, 2021). "Furthermore, leptin promoted colorectal cancer cell growth through the metallopanstimulin-1 (MPS-1)-dependent activation of the JNK signaling pathway." (PMID 33804101, 2021). "Meanwhile, recent studies have reported that leptin may be involved in colorectal cancer development and progression." (PMID 34650918, 2021). "Several studies illustrated that leptin might promote the invasion and distant metastasis of colorectal cancer." (PMID 35027962, 2021).
colorectal cancer (continued). "In the present study, we observed a statistically significant interaction between rs8050136 and plasma total adiponectin levels on colorectal cancer risk, rather than plasma leptin levels." (PMID 32053666, 2020). "This study is aimed at identifying leptin as a prognostic factor in colorectal cancer (CRC)." (PMID 32596369, 2020). "Therefore, we performed a two-stage case-control study to systemically evaluate single nucleotide polymorphisms (SNPs) of LEP and LEPR as a predictor of colorectal cancer risk in Chinese population." (PMID 23593308, 2013). "Ogunwobi and Beatles prove in their studies of leptin effect on colorectal cancer cells that leptin stimulates proliferation and inhibits apoptosis in human colorectal cancer cells, involving in those processes not only PI3 kinase but also JAK2 kinase and a transcription factor, the STAT3 protein." (PMID 22363883, 2011). "Although it has been suggested that in men, leptin may be associated with risk of colorectal adenomas other studies found decreased leptin serum levels in colorectal cancer patients." (PMID 21254741, 2010). "Mechanistically, the main effects of colorectal cancer prevention linked to physical exercise include the redirection of insulin-like growth factor (IGF), reduced inflammation, cell death via apoptosis, epigenetic changes, and regulation of leptin and ghrelin levels." (PMID 40095789, 2025). "In colorectal cancer macrophage-specific metabolites, itaconate can exert cancer-promoting effects in M2 macrophages through downregulation of peroxisome proliferator-activated receptor gamma (PPARΥ), a cellular pathway that is regulated by leptin and acts as a tumor-suppressing factor." (PMID 37686525, 2023). "Also in colorectal cancer, leptin affects macrophage polarization." (PMID 37686525, 2023). "Although genetic factors are not modifiable, control of plasma leptin and adiponectin levels might lead to a reduced risk of colorectal cancer even among carriers of risk alleles of the FTO gene." (PMID 32053666, 2020). "This discordance between plasma and tissue concentrations of adiponectin and leptin may, in part, explain why some studies have not observed associations between blood concentrations of adipokines and colorectal cancer risk." (PMID 25197277, 2014). "However, to date, these have been no studies addressing the role of genetic variants in Leptin gene family as colorectal cancer susceptibility factors in Chinese population." (PMID 23593308, 2013). "Blockade of ERK1/2 completely counteracts leptin-enhanced cell growth, suggesting that the ERK1/2 pathway is responsible for the increased proliferation of leptin-induced colorectal cancer stem cells." (PMID 37101229, 2023). "Leptin activates the JAK/STAT pathway by binding its receptor (OB-R) and thereby promotes the adhesion and invasion of colorectal cancer cells." (PMID 35634419, 2022). "In this study, we have investigated the degree of expression of LEP and LEPR in colorectal cancer (CRC)." (PMID 31592340, 2019). "Unconditional logistic regression analysis of colorectal cancer risks according to tertiles of zinc-α2-glycoprotein (ZAG), leptin, high-molecular-weight adiponectin (HMW-ADPN), and tumor necrosis factor-alpha (TNF-α) in all subjects." (PMID 29755407, 2018). "Furthermore, adipocytes also can produce polypeptide hormones (e.g., adiponectin and leptin), TNF-α, IL-6 and free fatty acid to mediate inflammatory response in colorectal cancer." (PMID 31963221, 2020). "In this study, we graded staining as ‘negative,’ ’low,’ and ’high’ (as elaborated in methodology) and observed presence of both LEP and LEPR in colorectal cancer (CRC) tissue samples in high intensity with high prevalence, 100% and 97.7% respectively (p < 0.01)." (PMID 31592340, 2019). "Leptin suppresses food intake by activating STAT3 phosphorylation in the hypothalamus; our previous study shows that PTPRT dephosphorylates STAT3 in colorectal cancers." (PMID 24949727, 2014).
colorectal cancer (continued). "Indeed, leptin and OBR expression is correlated with HIF-1α in endometrial and colorectal cancer, which suggests that HIF-1α may induce both." (PMID 23425972, 2013).
non-alcoholic fatty liver disease (76 papers, 2009 to 2026). "Furthermore, the supplementation of n-3 LCPUFAs decreased serum leptin levels caused by high-fat diet in a nonalcoholic fatty liver disease (NAFLD) model." (PMID 34692241, 2021). "Beyond cancer, leptin may play a role in other diseases associated with inflammation: In non-alcoholic fatty liver disease, leptin activates hepatic stellate cells (Ito cells), leading to upregulation of pro-inflammatory and pro-angiogenic effects, acting as an inducer of hepatic fibrogenesis." (PMID 34912237, 2021). "These outcomes demonstrate how cinnamon can combat leptin resistance and excessive fat storage, two characteristics of non-alcoholic fatty liver disease." (PMID 41141263, 2025). "In patients with non-alcoholic fatty liver disease, curcumin decreases plasma leptin and reduces leptin gene expression and signaling pathways in cell cultures." (PMID 36358567, 2022). "We draw special attention to the contribution of leptin to the non-alcoholic fatty liver disease (NAFLD) pathogenesis and its progression to more advanced stages of the disease as non-alcoholic steatohepatitis (NASH)." (PMID 33316927, 2020). "Evidence has suggested that HOMA-IR is associated with cardiovascular disease (CVD), muscle mass, nonalcoholic fatty liver disease (NAFLD), and several hormones, such as T4, TSH, leptin and adiponectin." (PMID 29108358, 2017). "One article noted that a high leptin-to-adiponectin ratio can be used as a noninvasive predictor of nonalcoholic fatty liver disease among obese adolescents." (PMID 26011530, 2015). "In addition, due to its close relationship with lipid metabolism, leptin has been correlated, both in experimental models and in experimental studies, with the presence of non-alcoholic fatty liver disease (NAFLD)." (PMID 38792501, 2024). "Studies on experimental models of non-alcoholic fatty liver disease (NAFLD) have revealed a potential dual role of leptin in NAFLD, which may have anti-lipogenic effects as well as pro-inflammatory and pro-fibrogenic actions." (PMID 39683601, 2024). "STAT3 plays a key role in the process of leptin resistance, and high leptin levels may be related to the increase of nonalcoholic fatty liver disease." (PMID 35154322, 2022). "In fact, hyperleptinemia is an independent predictor of nonalcoholic steatohepatitis (NASH) in obese humans, and the severity of steatosis, hepatocyte ballooning, as well as nonalcoholic fatty liver disease (NAFLD) activity scores correlate with serum leptin levels." (PMID 20150963, 2009). "Furthermore, according to an investigation on the effects of turmeric on serum glucose parameters and leptin levels in patients with nonalcoholic fatty liver disease (NAFLD), 46 individuals were given supplements of 3000 mg/day turmeric powder or placebo for 12 weeks." (PMID 40437595, 2025). "Recently, a protective effect of SELM on non-alcoholic fatty liver disease, cytotoxic effect of recombinant SELM on human glioblastoma cells, and SELM’s promotion of leptin signaling and thioredoxin activity have been reported." (PMID 38890329, 2024). "Non-esterified fatty acids, glycerol, tumor necrosis factors, leptin, resistin, and plasminogen activator inhibitor produced from adipose tissue all contribute to insulin resistance and NAFLD (nonalcoholic fatty liver disease) in the obese." (PMID 37616255, 2023). "SNORA71A targeted LEP participated in Jak-STAT signaling pathway, nonalcoholic fatty liver disease (NAFLD), and cytokine-cytokine receptor interaction." (PMID 33083486, 2020). "In non-alcoholic fatty liver disease (NAFLD) patients, increased severity of NAFLD correlates with higher levels of circulating leptin." (PMID 30718259, 2019). "The non-traditional cardiovascular risk factors that we studied were the following: hs-CRP, TG/HDL ratio, ApoA1, ApoB, ApoB/ApoA1 ratio, leptin, adiponectin, homocysteine, IL-2, IL-4, IL-6, IL-10, IL-17A, TNF-α and INF-γ, and non-alcoholic fatty liver disease (NAFLD)." (PMID 37892418, 2023).
non-alcoholic fatty liver disease (continued). "Moreover, LEP was enriched in multiple energy metabolism pathways, such as the AMPK signaling pathway, non-alcoholic fatty liver disease, and the JAK-STAT signaling pathway." (PMID 37958518, 2023). "Mice lacking B1Rs display an improvement on leptin and insulin sensitivity and are protected from non-alcoholic fatty liver disease (NAFLD) after a high-fat diet treatment." (PMID 36514072, 2022). "Furthermore, in the pathogenesis of non-alcoholic fatty liver diseases (NAFLD), leptin plays a key role in obesity development, the levels of which are usually elevated in the plasma of obese individuals, inducing HSC activation and promoting NAFLD development." (PMID 34830874, 2021).
ovarian cancer (76 papers, 2009 to 2025). A primary or metastatic malignant neoplasm involving the ovary. "Flow cytometry results have verified that leptin is associated with chemoresistance of ovarian cancer." (PMID 37605299, 2023). "The increased leptin in obese women has been associated with diagnosis of colon, breast, prostate and ovarian cancers in a previous study." (PMID 37496015, 2023). "Leptin has been implicated in regulating various malignant phenotypes of ovarian cancer through its involvement in the hypothalamic-pituitary-gonadal axis and multiple signaling pathways." (PMID 37190027, 2023). "The calculated formula with the combination of CA125, HE4, OPN, leptin and prolactin plasma levels surpasses each single marker in its diagnostic value to discriminate between benign and malignant ovarian tumors." (PMID 34530759, 2021). "High leptin levels have been associated with reduced progression-free survival in Middle Eastern women with epithelial ovarian cancer." (PMID 34440886, 2021). "In patients with ovarian cancer, increased leptin levels are associated with a higher level of circulating FSH." (PMID 28750624, 2017). "Among these OPG, IL-10, and leptin in the ascites of ovarian cancer patients were shown to be associated with shorter progression-free survival." (PMID 24093089, 2013). "Results of this study warrant examining the relationship between the risk of ovarian cancer and elevated leptin levels in obese women." (PMID 22968658, 2013). "Out of 120 cytokines analyzed OPG, IL-10, and leptin was found to be associated with worst prognosis in ovarian cancer patients." (PMID 24093089, 2013). "However, evidence on the association between circulating leptin and ovarian cancer risk or prognosis is limited." (PMID 37269192, 2023). "The results of a number of studies show that serum leptin and adiponectin levels are associated with an increase in the frequency of ovarian cancer in an inverse manner, i.e., increased leptin levels and decreased adiponectin levels have a pro-cancerogenic effect." (PMID 37190027, 2023). "Leptin, the most renowned adipokine, is one of the key risk factors for the several cancers, such as colorectal, esophageal, kidney, liver, pancreatic, thyroid, breast, and ovarian cancer." (PMID 38152619, 2023). "Elevated leptin levels are associated with poorer prognosis in ovarian cancer." (PMID 36230617, 2022). "Leptin has also been associated with chemoresistance in epithelial ovarian cancer." (PMID 36230617, 2022). "In ovarian cancer patients, high leptin levels are associated with poor treatment prognosis." (PMID 28861689, 2017). "There is some evidence that lower levels of leptin and higher levels of prolactin might be associated with increased risk of ovarian cancer." (PMID 29244844, 2017). "Additionally, the role of leptin and adiponectin in ovarian cancer has been linked." (PMID 37190027, 2023). "In particular, in patients with advanced ovarian cancer, rising IL-6 levels were inversely related with a decreased BMI, body weight, and lean body mass, and were also associated with a progressive decrease in leptin levels with the lowest values observed near the time of death." (PMID 33809200, 2021). "Leptin has been shown to promote cell migration and invasion in various in vitro studies on ovarian cancer." (PMID 38255203, 2024). "Increased leptin and Ob-R expressions have been observed in various malignant tissues, including breast, lung, colon, uterine, liver, and ovarian cancers." (PMID 38255203, 2024). "More than half of patients with epithelial ovarian cancer (EOC) in the Middle East demonstrated overexpression of leptin and its receptors, leading in a shorter overall survival." (PMID 38899007, 2024).